NCF1 (neutrophil cytosolic factor 1)
Diseases named in the same sentence as NCF1 in open-access papers (continued):
Sharing a sentence is not in itself a finding about the gene and the disease.
NCF1 also shares sentences with these, for which no sentence is quoted: endothelial dysfunction (13 papers); ischemia (10); cardiac hypertrophy (6); myocardial infarction (6); primary Sjögren’s syndrome (6); Cognitive impairment (5); heart failure (5); Stroke (5); prostate carcinoma (4); alcohol (3); autosomal recessive chronic granulomatous disease (3); cardiovascular disease (3); Cerebral ischemia (3); esophageal cancer (3); parasitemia (3); Parkinson disease (3); psoriatic arthritis (3); pulmonary fibrosis (3); systemic sclerosis (3); alcoholic liver diseases (2); Chronic colitis (2); diabetes mellitus type 1 (2); dyslipidemia (2); gout (2); Hypoglycemia (2); Insulin resistance (2); intracranial aneurysm (2); leukemia (2); ovarian carcinoma (2); pulmonary aspergillosis (2).
A further 101 diseases each share a sentence with NCF1 in 2 papers or fewer.